STAT3 (signal transducer and activator of transcription 3)
Diseases named in the same sentence as STAT3 in open-access papers (continued):
Sharing a sentence is not in itself a finding about the gene and the disease.
infection (continued). "Given the diverse biological functions of STAT3, further STAT3 SNP studies in other human infections may uncover that rs1053004 TT and rs1053005 AA genotypes or T-A haplotype could be a broad risk factor susceptible to diseases after infection." (PMID 34307193, 2021). "Hence, increased M. tuberculosis control during infection of stat3fl/fllysm cre mice is dependent on IL-17, but IL-17 neutralization did not increase the susceptibility to M. tuberculosis of mice with normal STAT3 function." (PMID 29338039, 2018). "In addition, PERK/ STAT3/NF-κB pathway could be a new therapeutic target to combat neuroinflammation associated with CA16 infection." (PMID 30186868, 2018). "However, late in infection and in sharp contrast to cells infected with S. Typhi, cells infected with S. Typhimurium showed a pattern of gene expression associated with the activation of STAT3 signaling." (PMID 28742135, 2017). "Cytokines utilizing the STAT3 signaling pathway including IL-6, IL-21, and IL-27 have been implicated in driving Tfh differentiation, but due to their partially compensatory pathways, separating the requirements for individual signals throughout infection has proved challenging." (PMID 25569154, 2015). "In addition, supplement of leucine or infection of Ad-S6K1 could rescue the reduction of phosphorylated STAT3 caused by stimulation of ghrelin in T cells." (PMID 25658305, 2015). "Although we found no compensatory upregulation of either of these factors in IL-6-deficient mice by quantitative PCR, it is likely that infection stimulates other factors that may, for example, activate STAT3 through the relatively promiscuous IL-6/IL-12 family of ligands." (PMID 24185641, 2014). "SCENIC analysis revealed Fos, Srf, and Stat3 as key transcription factors with elevated regulon activity and specificity following infection." (PMID 41594369, 2026). "This strategy is likely advantageous: IL-6 is often induced early in infection to recruit immune cells, but B. abortus can bypass this to activate STAT3 later, when dampening inflammation becomes critical for persistence." (PMID 41486271, 2026). "Host gene variants involved in trafficking (FYCO1 and RAB7A) and immune signaling (FOXA2, SFTPD, STAT3, and TET2) were associated with differential infection profiles." (PMID 41683583, 2026). "The fact that STAT3 inhibition affected the expression of most upregulated JAK/STAT target genes suggests STAT3 plays a major role in STAT-related transcriptional control during infection." (PMID 41115066, 2025). "Given our prior research establishing MCL-1 upregulation at the protein level during infection, we assessed the relevance of STAT3 in MCL-1 upregulation and apoptotic inhibition." (PMID 41115066, 2025). "In the context of ZIKV infection, the infection of primary retinal glial cell induces the phosphorylation of STAT3 at Tyr705." (PMID 41488475, 2025). "Briefly, THP-1 cells were incubated with cell-free E. chaffeensis (MOI 10) and harvested at 0, 24, 48, and 72 hpi to assess STAT3 activation throughout a full cellular infection cycle at early, mid, and late stages, respectively." (PMID 41115066, 2025). "Previous studies have confirmed that IL-6 and IL-1 stimulate hepcidin transcription through STAT3 signaling during infection and inflammation." (PMID 40298788, 2025). "In both lines, pathways associated with the host response to infection, including TNFα signaling via NF-κB, IL6/JAK/STAT3 signaling, and apoptosis, were significantly upregulated within 4 hours post-infection and remained elevated at 24 hours." (PMID 40766562, 2025). "The IL-6/STAT3 signaling pathway, activated by infection and other stimuli, can stimulate T and B lymphocyte proliferation and differentiation, promote synthesis of acute-phase response proteins, and trigger a cascade of inflammatory responses." (PMID 41137299, 2025).
infection (continued). "During infection with the psarA:gp130R168I mutant strain, STAT3 phosphorylation was significantly increased compared to infection with the psarA:gp130 strain." (PMID 40188438, 2025). "We infected THP-1 cells with these strains and measured phospho-STAT3 levels over the course of a 24-h infection." (PMID 40188438, 2025). "Pharmacological inhibition of STAT3 significantly reduced MCL-1 expression and increased caspase cleavage, implicating STAT3 as a regulator of anti-apoptotic signaling during infection." (PMID 41115066, 2025). "Studies have demonstrated that HBV, SGIV, ASFV, and HPV interact with STAT3 to facilitate their infection processes." (PMID 41488475, 2025). "Long-term management focused on infection prophylaxis significantly improves patient outcomes, though targeted therapies for STAT3-HIES require further development." (PMID 41458089, 2025). "THP-1 cells pretreated with C188-9 (10 μM) or dimethyl sulfoxide (DMSO) (0.1%) 3 h prior to infection with E. chaffeensis exhibited significantly less nuclear STAT3 than DMSO-treated cells at 72 hpi by immunofluorescent microscopy." (PMID 41115066, 2025). "Pharmacologic inhibition of STAT3 significantly decreased infection at 48 and 72 hpi, which was also confirmed in STAT3 KO cells." (PMID 41115066, 2025). "IL-6-induced STAT3 signaling upregulates hepcidin expression, sequestering iron to limit its availability to pathogens during infections while enhancing immune responses by promoting production of inflammatory mediators and acute-phase reactants." (PMID 41007630, 2025). "Transcriptomic analysis revealed significant upregulation of JAK/STAT target genes during infection, most of which were attenuated by treatment with a specific STAT3 inhibitor, C188-9." (PMID 41115066, 2025). "STAT3 phosphorylation and nuclear translocation were detected beginning 48 h post-infection, coinciding with upregulation of STAT3 target genes, including the anti-apoptotic gene MCL-1." (PMID 41115066, 2025). "Comparing infection-induced TCRab+ T cells, adults exhibited higher average STAT3, SOCS1, and SOCS3 expression, whereas STAT1 and STAT2 were elevated in cells from infected children, highlighting divergent IFN signaling with age." (PMID 40834853, 2025). "In parallel, signal transducer and activator of transcription 3 (STAT3) signaling has emerged as a key pathway exploited by BKPyV during infection." (PMID 41012683, 2025). "STAT3 was overactivated in periapical inflammatory macrophages and that inhibiting STAT3 activation effectively protects mice from infection-induced periapical inflammation." (PMID 40016707, 2025). "Multiple STAT family members were activated during E. chaffeensis infection, including STAT1, STAT3, STAT5, and STAT6; however, using a specific STAT3 inhibitor, most of STAT-related gene expression during infection was found to be associated with STAT3." (PMID 41115066, 2025). "STAT3 also modulates the infection process and regulates cell death in the context of infections by MuV, human metapneumovirus (hMPV), and Rift Valley fever virus (RVFV)." (PMID 41488475, 2025). "The IL-6/STAT3 pathway plays a significant role in regulating the immune response during these infections, particularly by modulating cytokine production, inflammatory cell recruitment, and acute-phase responses." (PMID 41137299, 2025). "The activation of intestinal CD8 + Tc1 cells in PINK1 KO mice at early stages after infection is illustrated by upregulation of Stat3 and Ccr5." (PMID 40404738, 2025). "Infection of the oral cell epithelium by P. gingivalis appears to promote the activation of key antiapoptotic pathways such as JAK1/STAT3, PI3K/Akt (protein kinase B), and Akt/FOXO1 signalling, as well as ATP-dependent apoptosis." (PMID 41228271, 2025). "In response to SarA transfection or during infection, we observed greater phosphorylation of STAT3 and upregulation of anti-inflammatory genes." (PMID 40188438, 2025).
infection (continued). "STAT3 is rapidly phosphorylated and thereby activated following infection of primary B lymphocytes with EBV; phosphorylated STAT3 is able to translocate to the nucleus causing transcriptional upregulation of a variety of genes including STAT3 in LCL." (PMID 40354417, 2025). "We demonstrated that STAT3 phosphorylation and nuclear translocation were significantly elevated by E. chaffeensis, particularly in later phases of infection." (PMID 41115066, 2025). "Together, these data suggest that STAT3 plays a critical role in E. chaffeensis replication or survival in host cells, particularly later in infection." (PMID 41115066, 2025). "Early in infection and lymphomagenesis, STAT3 is activated, promoting activation of caspase-7, Claspin degradation, and the consequent suppression of Chk1 phosphorylation and checkpoint activation." (PMID 41009395, 2025). "Phosphorylation of STAT1, STAT3, IκBα, and NF-κB p65 was detected as early as 6 hours post-infection (hpi) and peaked at 24 hpi." (PMID 41281739, 2025). "In contrast, SarA activation of STAT3 during infection led to high levels of phosphorylation by 3.5 hpi that were maintained through 24 hpi." (PMID 40188438, 2025). "Following infection with S. aureus, the activation of STAT3 occurs later than other signaling pathways, such as ERK and mTOR, leading to the delayed suppression of TFEB, a key regulator of lysosomal biogenesis and function." (PMID 40936092, 2025). "H. Pylori-infected C57BL/6 mice also developed SPEM 6 months after infection, accompanied by increased expression of IL-6, p-STAT3, and the proliferative marker Ki6711,40." (PMID 40520011, 2025). "While total levels of STAT3 remained consistent throughout the course of infection, activated STAT3 (phosphorylated at Y705) significantly increased at the 48 and 72 hpi time points." (PMID 41115066, 2025). "It plays a crucial role in post-infection tissue repair by stabilizing key transcription factors and signaling molecules such as STAT3 and AKT, thereby influencing immune and inflammatory responses, which in turn impact the onset and persistence of cough." (PMID 41044788, 2025). "Infection with MDV leads to a gradual increase in the levels of STAT3 protein and STAT3 phosphorylation in chicken embryonic fibroblasts (CEF), eventually inhibiting the ATR-Chk1 pathway and facilitating viral replication." (PMID 41488475, 2025). "Locally, astrocytes and microglia express hepcidin in response to inflammatory cytokines such as IL-6 that activates the JAK/STAT3 signaling cascade to drive hepcidin transcription during infection or inflammation." (PMID 41007630, 2025). "On the other hand, infection (the SFV group) significantly upregulated M1-linked TFs Stat1, Irf9 and Klf6 expression, as well as M2-linked Stat3 expression." (PMID 40547518, 2025). "In contrast, STAT3 exerts an immuno-protective effect during low-dose pH1N1 infection, highlighting the dose-dependent duality of STAT3’s role in IAV pathogenesis." (PMID 41488475, 2025). "Complete abrogation of STAT3 in KO cells prevented an increase in infection beyond that observed at 24 hpi, suggesting STAT3 is critical for ehrlichial infection at late phases." (PMID 41115066, 2025). "In contrast, STAT-3 expression levels were significantly elevated in duck cells, indicating infection with the same H5N1 strain had a less adverse effect in duck cells." (PMID 39281683, 2024). "The recurrent infections seen in patients with STAT3 HIES can be attributed in part to dysfunctional neutrophils, with impaired chemotaxis and decreased bacterial clearance." (PMID 39134362, 2024). "Whereas EBV triggered STAT3 phosphorylation, in particular between days 4 and 21 post-infection, a period in which LMP1 levels were markedly elevated and EBNA2 and 3C levels diminished." (PMID 38683861, 2024). "For this, the STAT3-GFP plasmid-transfected cells were infected with PR8 at the multiplicity of infection (MOI) of 1.0, 3.0, or 5.0." (PMID 39861822, 2024).
infection (continued). "The significant downregulation of genes like Stat3 and Vdac2, key mediators in necroptosis, points to a viral strategy to inhibit cell death that would otherwise limit infection spread." (PMID 39364165, 2024). "We also showed that inhibition of STAT3 activation at the beginning of KSHV de novo infection attenuated KSHV reactivation." (PMID 38240593, 2024). "After 6 h, cells were stained for nuclei and IAV nucleoprotein (NP) as an infection marker, and the nuclear translocation of STAT3-GFP was visualized by confocal microscopy." (PMID 39861822, 2024). "GC cells (AGS and MGC-803) infection assays revealed that this upregulation was mediated by the transcription factor STAT3, and activation of STAT3 by H. pylori promoted GRB7 expression in infected GC cells." (PMID 39360313, 2024). "The proinflammatory phenotype seen in our infection model is in line with the proposed predominantly anti-inflammatory role of STAT3 in myeloid cells." (PMID 37982695, 2024). "Taken together, CVB3 capsid protein VP1 directly activates STAT3 activation in the pancreas at an early phase of infection." (PMID 39201692, 2024). "STAT phosphorylation is a dynamic modification; preliminary testing suggested STAT3 was maximally phosphorylated at early times post infection (0.5 hpi) while STAT1 maximum phosphorylation occurred at 24 hpi." (PMID 38768227, 2024). "The expression levels of all genes except Stat2 and Stat3 increased rapidly from 0 to 4 h and peaked at 12 h after infection, with a subsequent gradual decrease until 16-h post-infection." (PMID 38753026, 2024). "A topical STAT3 inhibitor (Stattic) led to higher viral titers and more severe infection in mice that underwent scarification with ACAM2000TM, indicating that STAT3 inhibition impairs mechanisms by which keratinocytes control VACV infection." (PMID 38932162, 2024). "IL-6 is a cytokine with multiple functions that mediate the response to infection or injury and participates in tumourigenesis caused by activation of JAK2/STAT3 signaling." (PMID 39103836, 2024). "Compared with the STAT3-deficient mice, the percentage of CD11b+ AM in the BAL of uninfected animals and in the BAL and lungs at 36 h after infection was higher in the WT mice." (PMID 37982695, 2024). "Infections occur in approximately 20–50% of STAT3 GOF patients, with recurrent respiratory tract infections being the most common." (PMID 38535602, 2024). "In the current study, we found that CVB3 capsid protein VP1 induced p-STAT3 hyperactivation in the pancreases and hearts of mice at an early phase of infection." (PMID 39201692, 2024). "As infection progresses, the level of activated STAT3 is gradually decreased, and its reduced amounts are detected in IAV-infected cells at later infection timepoints due to IAV antagonizing the STAT3 activity." (PMID 39861822, 2024). "Bafilomycin A, a known inhibitor of endosomal trafficking, halved phospho-STAT3 levels, compared with the infection with vehicle alone." (PMID 37830871, 2023). "Monitoring pSTAT3 levels over time after wild-type infection revealed that phosphorylation of STAT3 began as early as 45 minutes after infection and continuously increased until it reached a plateau between 6 and 24 hours post-infection." (PMID 37830871, 2023). "In the present study, STAT3 appears up-regulated at 14 dpi while it seems unaltered by infection in all other time points." (PMID 38068937, 2023). "STAT3 activation continued to increase after 24 hours post-infection and reached a maximum by 22 days post-infection." (PMID 37830871, 2023). "The present study defines the activation of latent gene expression as a new function for STAT3 early after infection." (PMID 37830871, 2023). "STAT3C or wild-type STAT3 were introduced into iSLK cells via lentiviral vector infection, using different doses of the respective lentiviruses, and STAT3 expression and phosphorylation were monitored 2 days after lytic induction." (PMID 37983265, 2023).
infection (continued). "Previously, few studies have reported that STAT3 is mildly induced in macrophages upon LD infection." (PMID 37202419, 2023). "Chromatin immunoprecipitation (ChIP) assays further demonstrated enhanced recruitment of STAT3 to the IL-10 promoter upon LDPm infection." (PMID 37202419, 2023). "Infection with M81/∆gp110 strongly increased p-STAT3 levels, suggesting that this event occurs upon virus binding." (PMID 37830871, 2023). "Activating STING signals or inhibiting phosphorylated signal transducer and activator of transcription 3 (p-STAT3) in the early infection stage impaired Gal-9 promotion of EBV-infected B-cell outgrowth." (PMID 36622166, 2023). "The myeloid‐biased CD201− HSC population responds indirectly during an acute infection by sensing G‐CSF, increasing STAT3 phosphorylation, and upregulating LAP/LAP* C/EBPβ isoforms." (PMID 37846891, 2023). "This is in contrast to our observation in human and murine macrophages, where the infection resulted in augmented HIF1α levels, which impaired the activation of STAT3, resulting in inhibition of C. burnetii replication." (PMID 36793725, 2023). "Previous studies have shown that HSV-1 induces STAT3 phosphorylation in epithelial cells and T cells during early stages of infection, and that STAT3 acts as an important transcription factor inducing the expression of HSV-1 ICP0 and TK genes." (PMID 37655893, 2023). "Upon infection by P. gingivalis, both the JAK1/STAT3 and EMT phenotypes are activated, and tumor-associated neutrophils are recruited to promote OSCC progression via the CXCL2/CXCR2 axis." (PMID 38248096, 2023). "When BMDMs were exposed to DMI, the phosphorylated STAT3 levels were significantly downregulated at 18 h during infections of all three strains tested." (PMID 36882813, 2023). "STAT4 is indispensable for the induction of TH1 immune responses, while STAT3 is critical for the TH17 response against recurrent infections and establishment of T cell memory subsets." (PMID 36916966, 2023). "Whereas after 18 h following infection, the STAT-3 levels were also increased in female mice, indicating a time-dependent and sex-specific regulation of STAT-3." (PMID 35844510, 2022). "Further IHC results also revealed the significant progressive activation of Stat3 in both mouse and rat lungs during the late infection phase of AC." (PMID 35617354, 2022). "Meanwhile, we also found that 1,25(OH)2D3 reduced p-NF-κB, p-STAT1, and p-STAT3 protein levels induced by PEDV at 24 h post-infection." (PMID 36142545, 2022). "Immunoblot analysis suggested that Stat3 and p65 were notably and sustained activated in mouse lungs during the late infection phase." (PMID 35617354, 2022). "The incubation at 28°C prior to infection triggers a stronger STAT3 phosphorylation in vitro, which seems to correlate with a higher translocation of BepD into host cells." (PMID 35910598, 2022). "Early diagnosis of HIES and timely implementation of antimicrobials enable vigilance of skin or pulmonary infections, further preventing the occurrence of complications, especially for STAT3-HIES patients who lack the classical signs of infection." (PMID 36140582, 2022). "Infection of cardiomyocytes with the Tulahuén strain of T. cruzi induced an anti-apoptotic effect in an IL-6/STAT-3-dependent manner." (PMID 36389843, 2022). "Although S. aureus colonization and infection are key symptoms of STAT3-HIES and patients frequently require antibiotic prophylaxis or therapy, little is known about the molecular features of S. aureus in these patients." (PMID 35655107, 2022). "For one STAT3 patient WGS illustrated that infection and colonization occurred with different S. aureus isolates rather than one particular clone." (PMID 35655107, 2022). "We found that the infection significantly upregulated the expression of Acod1 and its downstream genes (Atf3, Stat3, Nfe2l2 and Nrf2, etc.)." (PMID 36618398, 2022).